PELP1 (proline, glutamate and leucine rich protein 1)
Diseases named in the same sentence as PELP1 in open-access papers (continued):
Sharing a sentence is not in itself a finding about the gene and the disease.
invasive breast carcinoma (2 papers, 2015 to 2023). A carcinoma that infiltrates the breast parenchyma. "Although PELP1 is localized to the cytoplasm in about 40% of invasive breast cancers, PELP1 localization in pre-malignant or high-risk tissues is not known." (PMID 25789479, 2015). "When compared to node-negative specimens, PELP1 expression is more prominent in invasive breast cancers and metastatic tumors." (PMID 37199805, 2023).
liver cancer (2 papers, 2024 to 2025). An epithelial or non-epithelial malignant neoplasm that arises from the liver. "PELP1 expression is upregulated in a variety of cancers, including breast, ovarian, endometrial, prostate, and liver cancers and serves as a prognostic factor for poor survival." (PMID 41463382, 2025). "Pharmacologic inhibition of PELP1 using SMIP34 also resulted in the downregulation of Myc, E2F, and liver cancer–specific genes." (PMID 39258975, 2024). "The gene set enrichment analysis revealed a negative correlation between PELP1-KD–regulated genes and the Myc, E2F, and liver cancer–pathway specific genes." (PMID 39258975, 2024).
medulloblastoma (2 papers, 2021 to 2024). A malignant, invasive embryonal neoplasm arising from the cerebellum. "PELP1 knockdown in medulloblastoma cells results in downregulation of NF-κB, including TRAF1 and IL-8, and expression of ECM-related genes MMP7, MMP9, and MMP1465, the latter of which is upregulated by microglia in late-stage NDD development." (PMID 34772945, 2021). "PELP1 signaling contributes to medulloblastoma progression by regulating the NF-κB pathway." (PMID 39258975, 2024).
metastatic tumors (2 papers, 2022 to 2023). "PELP1 signaling plays a critical role in TNBC metastases, and metastatic tumors exhibit increased PELP1 expression compared to node-negative specimens." (PMID 35205680, 2022).
non-small cell lung carcinoma (2 papers, 2021 to 2023). A group of at least three distinct histological types of lung cancer, including non-small cell squamous cell carcinoma, adenocarcinoma, and large cell carcinoma. "The expression of Proline-, glutamic acid-, and leucine-rich protein 1 (PELP1) has been reported to be dysregulated in non-small cell lung carcinoma, especially in lung adenocarcinoma (LUAD)." (PMID 34257530, 2021). "This review describes the mechanisms of targeted-drug resistance and newly identified non-small cell lung cancer targets (e.g., KRAS G12C, NGRs, DDRs, CLIP1-LTK, PELP1, STK11/LKB1, NFE2L2/KEAP1, RICTOR, PTEN, RASGRF1, LINE-1, and SphK1)." (PMID 36909198, 2023).
pancreatic cancer (2 papers, 2025). "Polyglutamylation of PELP1 in pancreatic cancer may influence its affinity for interacting proteins like LAS1L and SENP3 and the composition or conformation of the MLL1-WDR5 supercomplex, affecting histone modification and chromatin structure." (PMID 41463382, 2025).
acute appendicitis (1 paper, 2022). "The clinical relevance for PELP1 induction during inflammation was brought out from our primary studies like human acute appendicitis and DSS-induced mouse chronic ulcerative colitis models." (PMID 34774800, 2022). "To decipher the role of PELP1 in inflammatory diseases, we screened 69 paired human samples (N = 69) of normal and acute appendicitis." (PMID 34774800, 2022). "This is a clear evidence of high PELP1 expression in acute appendicitis." (PMID 34774800, 2022).
breast fibroadenoma (1 paper, 2025). "PELP1 is high in breast fibroadenoma, and an ER/HER-2-positive group had significantly higher PELP1 H-scores than their negative group." (PMID 41463382, 2025).
endocrine cancers (1 paper, 2015). "The Proline-, glutamic acid- and leucine-rich protein 1 (PELP1) is an estrogen receptor (ER) coactivator and a proto-oncogene known to be deregulated in endocrine cancers." (PMID 26247365, 2015).
endometrioid tumor (1 paper, 2013). A benign, borderline, or malignant epithelial tumor of the female reproductive system characterized by the presence of glands and/or cysts lined by neoplastic cells that resemble endometrial cells. "In our study-population, the majority of serous and endometrioid tumor tissues were PELP1 positive, whereas we observed a significantly reduced number of PELP1 expressing mucinous tumors (37.5%)." (PMID 23497172, 2013). "Prevalence of PELP1 expression in mucinous tumors was significantly lower (37.5%) compared to serous (85.7%) and endometrioid tumors (86.7%)." (PMID 23497172, 2013). "All undifferentiated carcinomas were PELP1 positive, as was the majority of serous and endometrioid tumors (85.7% and 86.7%, respectively), whereas the majority of mucinous tumors (62.5%) showed no nuclear PELP1 expression (p=0.02, Fisher’s exact)." (PMID 23497172, 2013).
idiopathic scoliosis (1 paper, 2016). A scoliosis with no known cause. "The aim of this study was to detect and assess the estrogen receptor (ESR) coactivator PELP1 expression within human paraspinal skeletal muscles in patients suffering from idiopathic scoliosis." (PMID 27045366, 2016).
Insulin resistance (1 paper, 2022). Increased resistance towards insulin, that is, diminished effectiveness of insulin in reducing blood glucose levels. "This region is located in the region of interaction between PELP1 and other proteins which have been reported to be significantly associated with fat deposition or insulin resistance." (PMID 35681846, 2022).
osteosarcoma (1 paper, 2021). A usually aggressive malignant bone-forming mesenchymal neoplasm, predominantly affecting adolescents and young adults. "Two estrogen-responsive element (ERE) half sites were reported in the promoter region of PELP1, and in the breast, endometrial as well as osteosarcoma model cancer cell lines, ERα or ERβ could be recruited to the promoter region of PELP1 and up-regulate the transcription of PELP1." (PMID 34257530, 2021).
ovarian tumor (1 paper, 2019). "Studies using ovarian tumor tissue arrays have shown that PELP1 was overexpressed 2–3-fold in 60% of ovarian tumors." (PMID 32117782, 2019).
salivary duct carcinoma (1 paper, 2013). An aggressive, high grade adenocarcinoma that arises from the salivary glands. "In salivary duct carcinoma, Pelp1 was reported to be localized in the cytoplasm." (PMID 24146754, 2013).
scoliosis (1 paper, 2016). A congenital or acquired spinal deformity characterized by lateral curvature of the spine. "Also, a correlation of PELP1 expression on the concave side with Cobb angle of the primary thoracic scoliosis was observed." (PMID 27045366, 2016). "Thus, the role of PELP1 in muscular cells of patients with scoliosis deserves deeper analysis." (PMID 27045366, 2016).
Thoracic scoliosis (1 paper, 2016). "In this study, we evaluated the recently described factor, PELP1, in the context of its possible involvement in the complex mechanism of onset and progression of spinal curvature within the frame of idiopathic thoracic scoliosis." (PMID 27045366, 2016). "A moderate correlation between PELP1 expression level on the concave side and the Cobb angle (r = 0.4; p<0.05) was noted, while it was not significant for the convex side of thoracic scoliosis (r = 0.4; p>0.056)." (PMID 27045366, 2016).
cancer (33 papers, 2010 to 2025). A tumor composed of atypical neoplastic, often pleomorphic cells that invade other tissues. "PELP1 is a known oncoprotein whose dysregulation is a hallmark of numerous cancers, particularly those driven by hormone signaling." (PMID 41465416, 2025). "The scaffolding oncogene PELP1, associated with cancer progression, was found to be upregulated in advanced ESCC stages." (PMID 38474224, 2024). "The oncogenic signaling of PELP1 is associated with the progression of various types of cancer, such as breast, endometrial, ovarian, salivary, prostate, lung, pancreas and colon cancers." (PMID 39258975, 2024). "Proline-, glutamic acid–, and leucine-rich protein 1 (PELP1) signaling is implicated in the progression of many cancers, although its specific contribution to the progression of HCC is not yet well understood." (PMID 39258975, 2024). "Oncogenic PELP1 signaling is implicated in the progression of several cancers, including breast, endometrial, ovarian, salivary, prostate, lung, pancreas, and colon." (PMID 35205680, 2022). "In conclusion, our study has presented PELP1 as an essential molecule for a number of important cellular processes, and its dysfunction is associated with various diseases, mainly cancer." (PMID 34774800, 2022). "The strong association between PELP1 and many human cancers has established PELP1 as a promising therapeutic target, however little is known about how the PELP1 scaffold coordinates its diverse cellular roles." (PMID 36351913, 2022). "We focused our attention on the causative role of PELP1 in inflammation and to identify its novel mediators responsible for inflammation-associated cancer progression." (PMID 34774800, 2022). "In the current study we found that moderate to high tumour nuclear DACH1 expression in the majority of cancer cells is compatible with functionally blocking PELP1 activity, reflected by its association with good prognosis." (PMID 24392136, 2014). "PELP1 is known to serve as an estrogen receptor alpha coactivator with prognostic value for several types of cancer and is linked to the GO biological process “response to hypoxia”." (PMID 20300185, 2010). "PELP1 oncogenic signaling has been linked to the progression of many cancers." (PMID 37853941, 2024). "PELP1 oncogenic signaling is implicated in the progression of several cancers including breast r." (PMID 35395812, 2022). "Understanding the regulatory mechanisms of PELP1 could help making better therapeutics to reduce the occurrence of several cancers associated with inflammation." (PMID 34774800, 2022). "A recent report suggests that cytoplasmic PELP1 induces macrophage activation, which promotes epithelial cell migration in a paracrine manner through inflammatory cytokines and chemokines via NF-κB, inducing protumorigenic signaling associated with cancer initiation." (PMID 34774800, 2022). "Furthermore, PELP1 has been associated with increased cell motility and invasion in cancer cells." (PMID 23497172, 2013). "This underscores the need for context-dependent interpretation of PELP1 as a biomarker and highlights the complexity of its role across cancer types." (PMID 41463382, 2025). "PELP1 is a component of autophagosomes, linking estrogen signaling, autophagy, and cancer cell fate via HRS, suggesting new therapeutic avenues for hormone-responsive cancers." (PMID 41463382, 2025). "The PELP1-TEX10-WDR18 complex functions as a ribosome biogenesis regulator, and PELP1 localization regulates the rate of ribosome synthesis, leading to cancer progression." (PMID 41463382, 2025). "Collectively, these findings indicate that PELP1 serves as a versatile chromatin regulator in cancer cells by recognizing histone modifications and via interactions with chromatin-modifying enzymes to influence transcription." (PMID 41463382, 2025). "Collectively, these findings suggest that either directly targeting PELP1 or its signaling complexes will have utility in treating PELP1 deregulated cancers." (PMID 41463382, 2025).
cancer (continued). "This review summarizes the most recent advancements in PELP1 biology, with a particular focus on the emergent oncogenic functions of PELP1 and its inhibitors for the treatment of cancer." (PMID 41463382, 2025). "The examination of the TCGA dataset utilizing the UALCAN database revealed a higher PELP1 expression in all cancer stages compared with normal liver tissues." (PMID 39258975, 2024). "Proline‐, glutamic acid‐, and leucine‐rich protein 1 (PELP1) is an oncogene commonly overexpressed in several cancers." (PMID 37853941, 2024). "Another instance involved is PELP1, a component in the Rix1 complex, identified as a proto-oncogene overexpressed in various cancer types, including breast, endometrial, ovarian, salivary, prostate, lung, pancreas, colon, and gastric cancer." (PMID 38633862, 2024). "The pivotal role of PELP1 in cancer has prompted the development of specific inhibitors, as discussed in subsequent sections." (PMID 38633862, 2024). "Analysis of the DepMap database's data showed that PELP1 is necessary for the survival of cancer cells." (PMID 37853941, 2024). "The scaffolding oncogene proline-, glutamic acid-, and leucine-rich protein-1 (PELP1) was found to be upregulated in advanced ESCC stages and associated with cancer progression." (PMID 38474224, 2024). "PELP1 signaling is shown to play a critical role in the cancer progression via its ability to activate multiple signaling pathways including hormonal signaling, cell cycle progression, ribosomal biogenesis, and DNA damage response." (PMID 37199805, 2023). "To further support the in vitro findings, we demonstrated expression of PELP1 in clinical samples comprising of normal–inflammatory–cancer progression disease spectra." (PMID 34774800, 2022). "These experiments support a model in which PELP1-WDR18 assembly removes PELP1 from the pool of ERα coactivators within cancer cells, thus decreasing ERα coactivation." (PMID 36351913, 2022). "PELP1 is a proto-oncogene whose expression is upregulated in many human cancers, but how the PELP1 scaffold coordinates its diverse cellular functions is poorly understood." (PMID 36351913, 2022). "Between CSF-2 and IL18R1, we chose to study CSF-2 as a potential target of PELP1 because of its proven role in cancer progression and as a secretory paracrine mediator." (PMID 34774800, 2022). "Results from preclinical studies with normal–inflammatory–tumor progression models demonstrated a progressive increase in the PELP1 expression, supporting this link between inflammation and cancer." (PMID 34774800, 2022). "PELP1 downregulation by miR-200-mimic or miR-141-mimic decreased the metastatic potential of cancer cells." (PMID 35682560, 2022). "Altogether, it can be concluded from our data that PELP1 is highly expressed in multiple cancer types (versus their corresponding normal)—especially in TNBC." (PMID 35205680, 2022). "Despite the existence of a large amount of literature linking PELP1 with human cancer, evidence in support of a contributing role of PELP1 in inflammatory responses still remains obscure." (PMID 34774800, 2022). "The aim of the current report is to explore the molecular mechanism of PELP1 induction during inflammation and its role in subsequent progression to cancer." (PMID 34774800, 2022). "In the current scenario, our work would present a platform emphasizing the novel role of PELP1 as a key oncogene in inflammation-driven cancers." (PMID 34774800, 2022). "Using TCGA datasets that contain gene expression profiles of tumor tissues, we discovered that PELP1 is highly expressed across diverse cancer types." (PMID 35205680, 2022). "This analysis can be better extended to other inflammation-driven cancers like pancreas, oral, and so on, which increases the potential of PELP1 as a clinical marker." (PMID 34774800, 2022). "The in vivo study on athymic and BALB/c mice presented strong evidence linking PELP1 in inflammation-directed cancer progression." (PMID 34774800, 2022).
cancer (continued). "Emerging evidences suggest the potential of PELP1 as an important driver of proliferation in cancer." (PMID 34774800, 2022). "Macrophages that overexpress PELP1 induces granulocyte–macrophage colony-stimulating factor secretion, which mediates cancer progression in a paracrine manner." (PMID 34774800, 2022). "PELP1 proteostasis has also been shown to be disrupted in cancer and appears to potentiate tumorigenesis." (PMID 36351913, 2022). "In the case of ESR1, in tissue obtained from cancer patients, there was a significant correlation with PELP1 and SRC expression." (PMID 34207568, 2021). "PELP1/AIB1-containing complexes in the cytoplasm function to promote advanced cancer phenotypes; including outgrowth of stem-like cells which are associated with E2-independent BC progression." (PMID 34528025, 2021). "Src axis couples ESR1 with PELP1 and depletion of c-Src inhibited the growth of therapy resistant cancers in in vitro models." (PMID 34207568, 2021). "In these human cancers, chlorpromazine can effectively inhibit growth, plate colony formation, migration, and invasion and decrease the protein expression of PELP1." (PMID 32117782, 2019). "Proline-, glutamic acid- and leucine-rich protein-1 (PELP1), a scaffolding oncogene, is highly correlated with cancer progression and outcomes for patients with advanced ESCC." (PMID 31501419, 2019). "PELP1/MNAR is a novel ER coactivator that exerts an essential role in ER’s actions and its expression is deregulated in hormone driven cancers." (PMID 29112114, 2017). "Of note, PELP1 expression was found to be deregulated in several cancers, and can be upregulated by estrogens and differentially regulated by selective estrogen receptor modulators." (PMID 29112114, 2017). "The prognostic significance of PELP1 varies among carcinomas, and seems dependent on the cellular context." (PMID 26472563, 2015). "Proline-, glutamic acid-, and leucine-rich protein 1 (PELP1), a coregulator of the estrogen receptors (ERs) alpha and beta, is a potential proto-oncogene in hormone dependent gynecological malignancies." (PMID 23497172, 2013). "In cancer cells, PELP1 seems to effect ER-mediated gene expression, subsequently influencing cell proliferation and differentiation." (PMID 23497172, 2013). "Comparable to our results, a correlation between ERbeta and PELP1 was observed, and PELP1 was a positive prognostic marker in the subset of ERbeta positive carcinomas." (PMID 23497172, 2013). "Emerging evidence implicates a functional role of ERα co-regulator proline glutamic acid and leucine-rich protein 1 (PELP1) in the oncogenic properties of cancer cells." (PMID 22812534, 2012). "Beyond its nuclear roles, PELP1 localizes to the nucleolus, where it interacts with RNA Polymerase I regulators, facilitating ribosomal biogenesis to meet the anabolic demands of hyper-proliferative cancer cells." (PMID 41465416, 2025). "PELP1 knockdown (KD) reduces cancer proliferation and therapy resistance by activation of KDM1." (PMID 41463382, 2025). "PELP1 is involved in chromatin remodeling by displacing histone H1 in cancer cells." (PMID 41463382, 2025). "Collectively, these findings support the utility of PELP1 as a biomarker for cancer prognosis." (PMID 41463382, 2025). "PELP1 subcellular distribution, along with its post-translational modification status, represents a potential regulatory mechanism for its coactivation of steroid receptors, both in normal and cancer tissues." (PMID 41465416, 2025). "The oncogene PELP1 is frequently overexpressed in a variety of cancers, including ECa." (PMID 37853941, 2024). "We explored the genome‐wide CRISPR/Cas9 proliferation screening database to determine whether PELP1 operates as a crucial gene in cancer cell survival." (PMID 37853941, 2024).